RN7SL449P (RNA, 7SL, cytoplasmic 449, pseudogene)
Gene: Miscellaneous RNA gene on chromosome 17 (57,618,108 to 57,618,393, forward strand). Ensembl gene ENSG00000242889.
Homologues: Orthologues: chimpanzee Metazoa_SRP (98% identical), dog Metazoa_SRP (70% identical). Paralogues in human: RN7SL1 (79% identical), RN7SL2 (79% identical), RN7SL3 (78% identical), RN7SL220P (77% identical), RN7SL788P (76% identical), RN7SL113P (76% identical), RN7SL543P (76% identical), RN7SL650P (76% identical), Metazoa_SRP (75% identical), RN7SL145P (75% identical), RN7SL296P (75% identical), RN7SL444P (75% identical), and 699 more.